LMX1A (LIM homeobox transcription factor 1 alpha)
Diseases named in the same sentence as LMX1A in open-access papers (continued):
Sharing a sentence is not in itself a finding about the gene and the disease.
gastric cancer (7 papers, 2012 to 2022). A primary or metastatic malignant neoplasm involving the stomach. "Qian and his colleagues demonstrated that LMX1A represses C-MYC expression by activating ANGPTL4 to function as a tumor suppressor in gastric cancer." (PMID 32751497, 2020). "Dong and his colleagues found that methylation-mediated inactivation of LMX1A and restoration of LMX1A induced cell apoptosis and suppressed anchorage-independent growth in gastric cancer." (PMID 32751497, 2020). "Our research group has showed that the LIM homeobox transcription factor 1 alpha (LMX1A) is inactivated in gastric cancers." (PMID 31557193, 2019). "Considering LMX1A as a transcription factor, a comparison of RNA-seq between gastric cancer cells (GCCs) and GCCs with LMX1A overexpressed was performed to identify genes transcriptionally activated by LMX1A." (PMID 31557193, 2019). "In this study, by identifying LMX1A-regulated genes using RNA sequencing in gastric cancer cell lines, we show that LMX1A exerts its tumor suppressive role partly through up-regulating ANGPTL4." (PMID 31557193, 2019). "As only ANGPTL4 was verified to be consistently up-regulated by LMX1A in two gastric cancer cell lines, we chose ANGPTL4 for further functional analysis." (PMID 31557193, 2019). "LMX1A gene has been reported to be hypermethylated in its promoter region in gastric cancer, ovarian cancer and cervical cancer, an important mechanism for loss of function of several tumor suppressor genes." (PMID 31557193, 2019). "Knockdown of LMX1A activated the Wnt/β-catenin-signaling pathway in gastric cancer." (PMID 33585699, 2021). "Since LMX1A was proved to contribute to ANGPTL4 expression in gastric cancer cells, it was concerned whether up-regulation of ANGPTL4 could also influence the tumor suppression role of LMX1A." (PMID 31557193, 2019). "Indeed, ANGPTL4, but not six other ANGPTL family members, showed co-expression with LMX1A in gastric cancer samples." (PMID 31557193, 2019). "Indeed, the role of LMX1A as a tumor suppressor has been unravelled in gastric cancer by us, and in ovarian cancer by others." (PMID 31557193, 2019). "Our previous study has shown that microRNA-9 (“miR-9”), being upregulated in human gastric cancer (GC), targets LMX1A to promote GC cell progression." (PMID 31915311, 2020). "microRNA-9 (“miR-9”), upregulated in human gastric cancer (GC) tissues, targets LMX1A (LIM homeobox transcription factor 1α) to promote GC cell progression." (PMID 31822638, 2019). "Thus, our results showed an upregulation of LMX1A is related with increased ANGPTL4 expression in gastric cancer cells, which could further contribute to the gastric tumor growth inhibition." (PMID 31557193, 2019). "Further, we investigated the relationship between LMX1A and ANGPTL4 in clinical gastric cancer samples by using The Cancer Genome Atlas (TCGA) Stomach Adenocarcinoma data collection." (PMID 31557193, 2019). "Considering LMX1A as a transcription factor, we proposed that LMX1A could contribute to the ANGPTL4 expression and inhibit tumor growth in gastric cancer." (PMID 31557193, 2019). "Both LMX1A and ANGPTL4 showed downregulated expression in gastric cancer samples." (PMID 31557193, 2019). "And In gastric cancer cells, such control mechanism was disrupted, the cancer cell increase the proliferation ability due to a uncontrolled overexpression of C-Myc and a lack of LMX1A expression." (PMID 31557193, 2019). "We confirmed that the expression of LMX1A was indeed dramatically reduced in gastric cancer samples compared to health group samples, following decreased ANGPTL4 expression, which suggested the positive-regulatory relationship between LMX1A and ANGPTL4 also existed in gastric cancer samples." (PMID 31557193, 2019). "More importantly, the expression of LMX1A is positively correlated with ANGPTL4, without including other family members in gastric cancer cell lines." (PMID 31557193, 2019).
ovarian carcinoma (5 papers, 2019 to 2021). A malignant neoplasm originating from the surface ovarian epithelium. "LMX1A downregulation is associated with ovarian cancer recurrence and poor overall survival." (PMID 33585699, 2021). "Moreover, LMX1A was reported to function as a tumor suppressor in cervical, gastric, and ovarian cancers, and its methylation was significantly associated with recurrence in bladder cancer and survival in stage I and II colorectal cancer patients." (PMID 32751497, 2020). "In ovarian cancers, LMX1A was reported to be hypermethylated, and its expression inhibited cell proliferation, migration, invasion, and colony formation." (PMID 32751497, 2020). "Chao and his colleagues reported that LMX1A could inhibit the EMT pathway by upregulating the epithelial marker CDH1 and downregulating the mesenchymal markers CDH2 and FN1 by repressing the EMT-related transcription factors SNAIL, SLUG, and SIP1 in ovarian cancer." (PMID 32751497, 2020).
hearing loss (4 papers, 2018 to 2025). "Patients with genetic variants of GJB2, SLC26A4, and LMX1A showed significantly higher detection of EH compared to other causes of hearing loss." (PMID 39373914, 2025). "The genetic variants of GJB2, SLC26A4, LMX1A are involved in inner ear development and associated with the occurrence of asymmetric sensorineural hearing loss." (PMID 39373914, 2025). "LMX1A is known for AD or AR nonsyndromic hearing loss, while COL2A1 is related to Stickler syndrome type 1 with hearing loss (MIM 108300) as well as various skeletal phenotypes." (PMID 33924653, 2021). "Here, we identified heterozygous pathogenic missense variants of LMX1A in two families of Dutch origin with progressive nonsyndromic hearing impairment (HI), using whole exome sequencing." (PMID 29754270, 2018).
bladder cancer (3 papers, 2019 to 2023). "Remarkably, VAX1 and LMX1A methylation were more frequently detected in urine samples from recurrent bladder cancer patients as compared to that of newly diagnosed bladder cancer patients, thus suggesting that the methylation of VAX1 and LMX1A was associated with bladder cancer recurrence." (PMID 37627900, 2023). "In addition, Zhao and his colleagues found that methylation of LMX1A could be used as an early diagnostic biomarker and was associated with recurrence in bladder cancer." (PMID 32751497, 2020). "The methylation frequency of eight genes (VAX1, ECEL1, KCNV1, LMX1A, PROX1, SLC6A20, TAL1, and TMEM26) was significantly higher in the urine of bladder cancer patients as compared to that of normal controls." (PMID 37627900, 2023). "Additionally, the promoter-hypermethylations of LMX1A, SOX1, and ZNF177 were previously reported in lung, stomach, and bladder cancers, respectively, by other groups." (PMID 31547144, 2019).
medulloblastoma (3 papers, 2024 to 2025). A malignant, invasive embryonal neoplasm arising from the cerebellum. "For example, SE heterogeneity analysis has identified SOX10 as the master regulator of the RTK I subtype in glioblastoma, HLX as the master regulator of the Group 3 subtype in medulloblastoma, and LMX1A as the master regulator of the Group 4 subtype in medulloblastoma." (PMID 40361105, 2025).
Intellectual disability (2 papers, 2018 to 2019). "LMX1A has previously been suggested as a candidate gene for intellectual disability, but our data do not support this, as affected subjects displayed normal cognition." (PMID 29754270, 2018).
type 2 diabetes (2 papers, 2013 to 2018). "The second set of genes LIM homeobox transcription factor 1 alpha (LMX1A), solute carrier family 30 member 8 (SLC30A8) is associated with insulin metabolism and resistance, a feature of some patients in whom type 2 diabetes is an accompanying comorbidity of vestibular neuritis." (PMID 30079052, 2018).
Ataxia (1 paper, 2025). Ataxia refers to impaired coordination of voluntary muscle movement. "Double-mutant Lmx1b/Lmx1a mice do not develop a cerebellum, a condition associated with ataxia." (PMID 40170168, 2025).
autism (1 paper, 2021). Persistent deficits in social interaction and communication and interaction as well as a markedly restricted repertoire of activity and interest as well as repetitive patterns of behavior. "After 10 days of differentiation, nearly 100% of mFPPs from both control- and autism-iPSCs were positive for LMX1A, an essential transcription factor required for defining a midbrain identity." (PMID 32826066, 2021).
autosomal dominant nonsyndromic hearing loss 7 (1 paper, 2026). An autosomal dominant nonsyndromic deafness that is characterized by progressive high-tone hearing loss and has material basis in variation in the chromosome region 1q21-q23. "Pathogenic variants in the LIM-homeodomain transcription factor LMX1A represent a rare yet critical etiology for autosomal dominant nonsyndromic hearing loss 7 (DFNA7) and less frequently, its autosomal recessive counterpart (ARNSHL)." (PMID 42253511, 2026).
CHARGE syndrome (1 paper, 2021). CHARGE syndrome is a multiple congenital anomaly syndrome characterized by the variable combination of multiple anomalies, mainly Coloboma; Choanal atresia/stenosis; Cranial nerve dysfunction; Characteristic ear anomalies (known as the major 4 C's). "Among them, LMX1A is required for proper ear histogenesis and morphogenesis, and loss of hearing is a pivotal defect of the CHARGE syndrome." (PMID 33948885, 2021).
chordoma (1 paper, 2023). Chordomas are rare malignant tumors arising from embryonic remnants of the notochord in axial skeleton. "Genes marked on the volcano plot were either implicated earlier in chordoma biology (e.g. keratins—KRT8, KRT18, KRT19, TBXT, LMX1A, and EGFR) or identified by outstanding p-value (e.g. IL11, CD24), high absolute fold-change (e.g. GABRA1) or DMR result (e.g. MNX1)." (PMID 37434245, 2023).
colon adenocarcinoma (1 paper, 2019). "Moreover, the correlation analysis of the differential methylation and expression levels of LMX1A, SOX1, ZNF177 and NKX6.1 in colon adenocarcinoma patients was based on data derived from the MethHC database." (PMID 31547144, 2019).
colorectal cancer (1 paper, 2020). A primary or metastatic malignant neoplasm that affects the colon or rectum. "We also found that LMX1A, in combination with NKX6.1, SOX1, and ZNF177, could serve as a stage-independent prognostic marker in colorectal cancer." (PMID 32751497, 2020).
congenital hydrocephalus (1 paper, 2009). Hydrocephalus that is present at birth. "Furthermore, mutations in two different genes (Foxc1 and Lmx1a) were found to be responsible for two hydrocephalus mouse models, congenital hydrocephalus (ch) and dreher (dr) mice, respectively." (PMID 19924295, 2009).
Lissencephaly (1 paper, 2019). A spectrum of malformations of cortical development caused by insufficient neuronal migration that subsumes the terms agyria, pachygyria and subcortical band heterotopia. "Thus, Lmx1a and Lmx1b function redundantly to maintain lissencephaly in the mouse, and simultaneous loss of these genes is sufficient to induce gyrification of the mouse cortex." (PMID 31729356, 2019).
lung carcinoma (1 paper, 2020). "To elucidate the role of LMX1A in lung cancer, we analyzed the A549, H1299, H23, CL1-0, CL1-3, H358, and H647 cell lines for endogenous LMX1A expression." (PMID 32751497, 2020). "Treatment of lung cancer cells with the demethylating agent 5-aza-2’-deoxycytidine restored LMX1A expression." (PMID 32751497, 2020). "In this study, we used public databases, methylation-specific PCR (MSP), reverse transcription PCR (RT-PCR), and bisulfite genomic sequencing to show that LMX1A was downregulated or silenced due to promoter hypermethylation in lung cancers." (PMID 32751497, 2020). "The purpose of this study was to investigate the epigenetic regulation and biological function of LMX1A in lung cancer." (PMID 32751497, 2020). "Then, we analyzed the methylation level and mRNA expression of LMX1A in lung cancer cell lines." (PMID 32751497, 2020). "In summary, the current study demonstrated that LMX1A functions as a tumor suppressor partly by repressing EMT, angiogenesis, and ECM remodeling in lung cancer." (PMID 32751497, 2020). "In the lung cancer cell lines H23 and H1299, overexpression of LMX1A did not affect cell proliferation but suppressed colony formation and invasion." (PMID 32751497, 2020).
nail-patella syndrome (1 paper, 2018). A rare hereditary patellar dysostosis characterized by nail hypoplasia or aplasia, aplastic or hypoplastic patellae, elbow dysplasia, and the presence of iliac horns as well as renal and ocular anomalies. "Heterozygous loss-of-function variants of LMX1B (MIM: 602575), a paralog of LMX1A, have been associated with nail–patella syndrome in human (NPS, MIM: 161200)." (PMID 29754270, 2018).
non-small cell lung carcinoma (1 paper, 2020). A group of at least three distinct histological types of lung cancer, including non-small cell squamous cell carcinoma, adenocarcinoma, and large cell carcinoma. "In this study, we found that LMX1A was methylation-silenced in non-small cell lung cancer." (PMID 32751497, 2020). "Furthermore, LMX1A inhibits non-small cell lung cancer (NSCLC) cell invasion partly through modulation of EMT, angiogenesis, and ECM remodeling." (PMID 32751497, 2020).
pancreatic ductal adenocarcinoma (1 paper, 2020). An infiltrating adenocarcinoma that arises from the epithelial cells of the pancreas. "Tsai and his colleagues reported that the higher expression of LMX1A was strongly correlated with the histologic grade and pathologic stage of pancreatic ductal adenocarcinomas." (PMID 32751497, 2020).
schizophrenia (1 paper, 2017). A major psychotic disorder characterized by abnormalities in the perception or expression of reality. "Interestingly, three SNIPs in LMX1 A and one in LMX1B were found associated with schizophrenia, and were the same as those previously identified in PD42." (PMID 29038581, 2017).
spine chordoma (1 paper, 2022). "As for transcriptome biomarkers, LMX1A is dominant in skull base chordoma, and SALL3 is unique to spine chordoma." (PMID 36185236, 2022).
sudden sensorineural hearing loss (1 paper, 2025). Sensorineural hearing loss which develops suddenly over a period of hours or a few days. "In patients with idiopathic hearing loss and sudden sensorineural hearing loss, although not as high as patients with genetic variations of GJB2, SCL26A4, and LMX1A, the ratios of EH detected in HYDROPS MRI was relatively high, reaching 20–40%." (PMID 39373914, 2025).
tumor (17 papers, 2012 to 2025). "Other genes, such as LIM homeobox transcription factor 1α (Lmx1a), have been associated with cancer but this appears to act as a tumour suppressor, and thus the effect of its downregulation by JQ1+ on the growth of AtT20 cells is unknown." (PMID 34223822, 2021). "Tumor cell groups were assigned based on chromatin accessibility of genes expressed in tumor cells, including Hes5 and Sox2, whereas regulatory regions of Lmx1a and Lmx1b were accessible only in tumor cell groups." (PMID 40128799, 2025). "Consistently, RT-qPCR and RNA-seq studies using tumor bulk showed significantly increased Lmx1a and Lmx1b expression, along with increased Sox2 levels, compared to wild-type CP from birth to adult stage." (PMID 40128799, 2025). "Conversely, Sox2 loss resulted in significantly reduced LMX1A expression, whereas LMX1B was lost in Sox2-deficient tumor cells after birth." (PMID 40128799, 2025). "After loss of Sox2, LMX1A and Ki-67 expression was greatly reduced, whereas the expression of LMX1B was abolished in Sox2-deficient CP tumor cells from Lcre;NICD1;Sox2cko embryos." (PMID 40128799, 2025). "RNAscope studies of 3 human CP tumors (1 grade 1 tumor, and 2 grade 2 tumors) revealed co-expression of HES5 and LMX1A in a fraction of tumor cells." (PMID 40128799, 2025). "Consistently, immunofluorescence also showed that LMX1A was expressed in a subset of CP tumor in humans." (PMID 40128799, 2025). "The authors that demonstrated the knockout of LMX1A increased the cell viability and cell proliferation, reinforcing the role of LMX1A as a tumor suppressor in GC." (PMID 36360266, 2022). "Based on these in vitro studies, a xenograft animal model should be established to clarify LMX1A’s tumor suppressor role in NSCLC in vivo." (PMID 32751497, 2020). "Taken together, these data demonstrated that LMX1A is inactivated through promoter hypermethylation and functions as a tumor suppressor." (PMID 32751497, 2020). "Our data demonstrated that LMX1A is epigenetically regulated and functions as a tumor suppressor in non-small cell lung cancer (NSCLC)." (PMID 32751497, 2020). "All together, these data suggested that LMX1A functions as a tumor suppressor partly by regulating EMT-related genes." (PMID 32751497, 2020). "The LMX1A-ANGPTL4-C-Myc axis is proposed to be one of the mechanisms that explains the tumor suppressive role of LMX1A." (PMID 31557193, 2019). "In general, our results showed that LMX1A exerts its tumor suppressive role by activating ANGPTL4 to inhibit C-Myc." (PMID 31557193, 2019). "Although the tumor suppressor role of LMX1A has long been proposed by us as well as others, the underlying mechanism remain unrevealed." (PMID 31557193, 2019). "The results showed that while LMX1A overexpression expectedly inhibited tumor growth, the inhibitory effect was reversed by knockdown of ANGPTL4." (PMID 31557193, 2019). "What’s more, knockdown of ANGPTL4 rescued the tumor suppressive phenotype of LMX1A overexpression, which indicated that LMX1A upregulates ANGPTL4 to exert its role." (PMID 31557193, 2019). "To identify genes that contribute to LMX1A’s tumor suppressive role, we sought to identify LMX1A-regulated genes." (PMID 31557193, 2019). "Taken together, our results indicate that the tumor suppressive role of LMX1A at least partly dependent on the up-regulation of ANGPTL4." (PMID 31557193, 2019). "Our previous study has demonstrated that LMX1A functions as a tumor suppressor, inhibiting GC cell survival and proliferation." (PMID 31822638, 2019). "LMX1A is mainly considered as a tumor suppressor in various cancers." (PMID 33585699, 2021). "In addition, LMX1A served crucial functions in tumor invasion and epithelial-mesenchymal transition." (PMID 32751497, 2020). "We found that LMX1A inhibited c-Myc expression to exert tumor suppressive function in GC cells." (PMID 31915311, 2020). "Our group has shown that LMX1A exerted tumor-suppressive functions in GC cells." (PMID 31915311, 2020).